STAT1 (signal transducer and activator of transcription 1)
Diseases named in the same sentence as STAT1 in open-access papers (continued):
Sharing a sentence is not in itself a finding about the gene and the disease.
infection (continued). "When infected with rMA15 virus, STAT1−/− mice showed higher peak virus titers in the lungs at day 2 (∼108 pfu/g) that remained as high as >106 pfu/g at day 9 post-infection, while 129 WT mice had cleared the virus by 9 days." (PMID 20386712, 2010). "By 9 days post-infection, the inflammation continued to increase in STAT1−/− mice while lung inflammation was subsiding in 129 WT, IFNAR1−/− and IFNGR−/− infected mice." (PMID 20386712, 2010). "In contrast, infection of STAT1−/− mice resulted in severe disease, high virus titer, extensive pulmonary lesions and 100% mortality by day 9 and 30 post-infection with rMA15 or Urbani viruses, respectively." (PMID 20386712, 2010). "In stark contrast and consonant with earlier reports, STAT1−/− mice infected with Urbani virus initially gained weight as 129 WT mice did, through day 12 post-infection." (PMID 20386712, 2010). "Virus replication in the STAT1-/- DCs (open squares) was approximately 1,000-fold higher at 48 hrs post-infection than in DCs from 129SVE mice (solid squares)." (PMID 19439086, 2009). "STAT1-deficient mice are highly sensitive to infection by microbial pathogens and viruses including HSV-1, which replicates to approximately 1000-fold higher titers in the eyes of STAT1-/- mice compared to wt mice." (PMID 19439086, 2009). "HIV-1 induced STAT1 phosphorylation 3 days after infection, and the phosphorylation persisted for 4 additional days." (PMID 19404407, 2009). "rSeVhP infection prevents nuclear translocation of STAT1 upon IFN stimulation, indicating that hPIV1 C protein can inhibit the Jak/STAT pathway in murine cells." (PMID 21994561, 2009). "STAT1 activation in MDM by HIV-1-infection suggests there are type I IFNs in the culture supernatant acting in autocrine and paracrine manner." (PMID 19404407, 2009). "This time point of infection was chosen since we observed considerable inhibition of IFN-induced STAT1 phosphorylation in the course of infection." (PMID 18989459, 2008). "A predominant Th1 immune response was observed during infection, as 6 of 11 investigated Th1 associated genes, including TNF, IFNG, and some IFNG-signaling responsive genes (SOCS1, STAT1, WARS and IRF1), were strongly up-regulated at 24 hpi and/or 48 hpi." (PMID 18811943, 2008). "Studies of MNV pathogenesis reveal an important role for interferon (IFN) and STAT-1 mediated innate immunity in resistance to infection and MNV induced lethality." (PMID 19079577, 2008). "For efficient transfection of the expression constructs we used the highly susceptible cell line HEK293 that also exhibits impaired IFNβ-induced STAT1 phosphorylation at later stages of infection." (PMID 18989459, 2008). "In contrast, infection of SOCS-3 knock out cells resulted in strongly elevated phosphorylation of STAT1 in a sustained fashion." (PMID 18989459, 2008). "Similar to in vitro data, infection with B.anthracis in vivo results in only mild induction of IFN signaling as determined by STAT1 phosphorylation." (PMID 17710136, 2007). "In the absence of IFNβ signaling, studies have observed reduced levels of STAT1, STAT2, IRF1, and IRF7 in cells maintained in sterile environment, making them less responsive to interferon signaling and more susceptible to subsequent infection." (PMID 41525418, 2026). "The key transcription factor STAT1 was significantly activated upon infection." (PMID 41874176, 2026). "At all doses tested, Ifnar1-/- mice succumbed to lethal infection sooner than Stat1-/- mice." (PMID 40694555, 2025). "However, in our study, in the high-dose infection group, elevated STAT1 and ISG expression were accompanied by a marked upregulation of pro-inflammatory cytokines, including IL-6 and TNF-α." (PMID 40941331, 2025). "Interestingly, phosphorylation of IRF3 increased between 4 and 8 h post-ASFV infection and gradually decreased thereafter, while phosphorylation of STAT1 continued to rise up to 24 h." (PMID 40500801, 2025).
infection (continued). "Indeed, results have also proved that STAT-1 plays a critical role in the regulation of E. coli invasion and infection in the uroepithelial cells, especially those pretreated with glucose." (PMID 40283465, 2025). "Notably, NVA17 achieved complete protection against lethal infection in this immunocompromised STAT1+/− model, unequivocally demonstrating its robust efficacy." (PMID 41441659, 2025). "Astrocytes respond to infection and contribute to the immune response by releasing cytokines and chemokines, limiting parasite replication via activation of STAT‐1 signaling, and increasing extracellular glutamate concentrations through a diminished capacity for glutamate uptake." (PMID 40635167, 2025). "In contrast, rWT infection induced weaker and delayed p-Stat1 detection." (PMID 40838727, 2025). "Transient IFNγ-STAT1 inhibition prevents TI signatures and splenic infection resistance." (PMID 39819562, 2025). "Furthermore, compared with infection with ASFV-WT, infection with ASFV-Δ4R increased the phosphorylation of STAT1 and STAT2 following IFN-β treatment." (PMID 40618140, 2025). "Surprisingly, rapidly after infection (2 dpi), Lepr-deficient, T2DM mice exhibit an increased expression of IFNβ, but not IFNα, with apparent activation of JAK and phosphorylation of STAT1 (pSTAT1) leading to the expression of interferon-stimulated genes (ISGs)." (PMID 40125513, 2025). "Thus, we have now demonstrated that STAT1 competency in hematopoietic cells specifically is required to protect against lethality following infection with two flaviviruses." (PMID 40694555, 2025). "In addition, rotavirus was associated with STAT1/STAT2 inhibition, which decreased antiviral response in early infection, through the activity of NSP1." (PMID 38791551, 2024). "Our new data showing that CebN binds NUPs and Rae1 and perturbs nuclear translocation of STAT1 may be the missing link needed to understand how C.t. establishes a persistent infection in spite of robust IFN-γ production." (PMID 38712050, 2024). "Interestingly, we observed the downregulation of genes such as Tnf-α, Il18, Mx1, Rig1, Pkr, Stat1, Stat2 and Irf9, which appear to be hallmarks of hRSV persistence in contrast to the acute infection." (PMID 39296294, 2024). "Inhibition of STAT1 phosphorylation by Rv2347c might be related to IFNAR, and knockdown of IFNAR enhances the survival of susceptible mice in response to infection with hypervirulent strains HN878 and H37Rv." (PMID 39313213, 2024). "During late infection, STAT1 was cleaved at aspartic acid 694 in a caspase-dependent manner." (PMID 38018976, 2024). "Ifnar1−/− and Ifngr1−/− mice were separately infected with PbA, and WB analysis of the mouse brainstems showed that the levels of p-STAT1 and PD-L1 in knockout mice increased to a certain extent after infection but were lower than those of the control littermates." (PMID 38715061, 2024). "We found that both RNA and protein levels of STAT1 were upregulated after infection (p < 0.0001)." (PMID 38397085, 2024). "We focused on examining how impaired STAT1 expression on CD11c+ cells affected innate cell differentiation, T cell re-expansion, and fungal dissemination in vaccinated mice at day 4 and day 7 post-H99 infection." (PMID 39324785, 2024). "We analyzed the protein levels of STAT1 and p-STAT1 at 48 and 72 h after infection." (PMID 38018976, 2024). "Intriguingly, genes such as Ifi204, Irgm1/2, Nos2, Gbp3/7, Usp18, Irf7, Stat1, and Isg15, which were upregulated in response to infection in cells treated with siR_Ctrl, showed decreased upregulation in cells treated with siR_Nostrill following infection." (PMID 39040107, 2024). "This may indicate that the antiviral response induced by C. sorokiniana in rotavirus-infected cells was mediated by IFN-α and IFN-γ in the pre-infection assays and STAT1/STAT2 in the post-infection assays and regulated by SOCS3 in both assays." (PMID 38791551, 2024).
infection (continued). "In this regard, we observed an increased level of mRNA expression of IFN-γ and STAT1 in pre-infection with the probiotic alone or with the microalgae, which was associated with an improvement of antiviral cellular response, in comparison with rotavirus-infected cells alone." (PMID 38791551, 2024). "Infection prevention for STAT1 GOF depends on the clinical presentation, which is quite variable." (PMID 39599507, 2024). "Our observation that H37Rv-INH-R infection caused the highest ISG expression levels suggests a stronger induction of STAT1 as a result of cGAS-STING activation, rather than TLR2-MyD88 activation." (PMID 39597535, 2024). "Intriguingly, while UL138 expression reduced IFNB1 and CXCL10 accumulation downstream of cGAS-STING-TBK1, it has also been reported to enhance the expression of some interferon stimulated genes (ISGs) at late times during productive infection, presumably by promoting the activation of STAT1." (PMID 38932169, 2024). "The pancreatic protein levels of p-STAT1 and STAT1 were unchanged during 7 days of infection." (PMID 39201692, 2024). "Instead, the decrease in the MHV68 latent reservoir observed in mice with B cell-specific STAT1 deficiency was due to attenuated infection of germinal center B cells that are independent of marginal zone B cells in their differentiation trajectory." (PMID 39440973, 2024). "In addition, Ddx58 and cGAS, which encode factors for virus sensing, Stat1, Stat2, and IFN regulatory factor 7 and 9 mRNA levels were also induced at the initial stage of infection." (PMID 38125412, 2023). "In the clinical case with STAT1 GOF linked to HLH, the hyperphosphorylated status of STAT1 was associated with a persistent overactivity of APCs, previously activated by innate immune receptors in the context of an infection." (PMID 37187762, 2023). "However, upon treatment with IFN-β, only bystander cells induce STAT1 translocation during infection with WT virus, whereas ΔORF6 virus-infected cells now show translocation." (PMID 37377442, 2023). "In fact, most of the chemokines and cytokines upregulated in Stat1 knockout mice after infection are driven by NF-κB that binds to κB sites in promoter sequences at gene loci that could easily be explained by TLR activation." (PMID 37228668, 2023). "In the present study, neonates challenged with E. coli had attenuated hypomethylation of CpGs, yet juveniles were poised to quickly respond to E. coli with dynamic hypomethylation of CpGs and marked induction of Stat1 and interferon response genes at 72 h post-infection." (PMID 36922640, 2023). "The induction of total STAT1 in WT infection may be the result of feedback in STAT1 signaling as STAT1 transcripts and protein levels are increased by pSTAT1 signaling." (PMID 37289831, 2023). "STAT1 is fundamentally important for host defenses against A. phagocytophilum infection, leading to macrophage activation and inevitably, markedly improved control of infection." (PMID 37228668, 2023). "Again, limited infection was observed in wild-type enteroids, but substantially greater viral RNA levels (~ 22.4-fold increase at 96 hpi) were measured in the supernatants of STAT1-/- enteroids." (PMID 37749080, 2023). "While the overall levels of STAT1 exhibited a slight increase at 16 and 20 h post-infection in cells infected with rIBV-ΔPL1pro-N compared to rIBV, the expression of p-STAT1 was notably elevated during these post-infection times in the rIBV-ΔPL1pro-N infected cells, peaking at 20 h post-infection." (PMID 38087313, 2023). "Lymphocyte antigen, caspase 3 and signal transducer and activator of transcription 1 (STAT1) were either downregulated or undetected while leukocyte surface antigen and neutrophilic granule were upregulated as the host recovered from the infection and during the latent period of oocyst shedding." (PMID 37759313, 2023).
infection (continued). "However, at 20 h post-infection, the nuclear expression level of p-STAT1 was significantly higher in rIBV-ΔPL1pro-N infected cells compared to rIBV-infected cells." (PMID 38087313, 2023). "Stat1 null mice depleted of CD8+ T cells die within two weeks of infection." (PMID 37896889, 2023). "It is noteworthy that STAT1 could also be observed in the nuclei of FJzz1-infected cells, implicating the induction of STAT1 nuclear translocation by FJzz1 infection." (PMID 35958569, 2022). "We found that IFN-β is the main inducer of the STAT1/2-associated antiviral state in RSV-infected A549 cells and that both IFN-β and IFN-λ are simultaneously necessary for building maximum protection against subsequent infection with IAV." (PMID 36326278, 2022). "Thus, our study reveals a bifurcated proviral role of T cell-intrinsic STAT1 during MHV68 infection, where it serves to facilitate infection of germinal center B cells yet restrict systemic IFN gamma production." (PMID 35968944, 2022). "STAT1(−) mice, however, were found to have high sensitivity to this infection." (PMID 36423105, 2022). "Moreover, the BoHV-1 protein VP8 downregulates the type I IFN pathway early in infection by interacting with STAT1 to prevent nuclear accumulation of STAT1." (PMID 35259065, 2022). "In addition, DExD/H-Box Helicase 58 (DDX58, also known as Retinoic acid-inducible gene I (RIG-I)), and STAT1, which is a key component of bacterial and viral sensing pathways, were only statistically altered during infection in KO DCs." (PMID 36131943, 2022). "Quite unexpectedly, we also found that T-cell intrinsic STAT1 expression restricts systemic IFN gamma production during MHV68 infection, with corresponding effects on viral control in the peritoneum and persistent replication in the lungs of chronically infected mice." (PMID 35968944, 2022). "Moreover, the IFN-γ-STAT1 signalling axis was active in human organoids and efficiently prevented the induction of c-Myc upon infection." (PMID 36155135, 2022). "Interestingly, the protective effect by deletion of Stat1 in Casp8ΔIECmice was stable throughout the course of infection." (PMID 34497340, 2022). "During the infection, STAT1 is a TLR-mediated antibody response and B cell differentiation." (PMID 35563088, 2022). "Additionally, the same results were found by other researchers, who reported that the expression of STAT1 is induced by Poly I:C, and upon infection, its expression was found to be significantly enhanced as compared to the control." (PMID 36611649, 2022). "SARS-CoV-1 virus has previously been shown to inhibit STAT1 translocation, and we hypothesized that the cytoplasmic pattern may be due to an inhibition of translocation after infection." (PMID 36324747, 2022). "Thus, in the context of MHV68 infection, T cell-intrinsic STAT1 expression is likely to act in trans, by suppressing the expansion and/or IFN gamma expression by other immune populations, such as NK cells and dendritic cells." (PMID 35968944, 2022). "STAT1 depletion rescued c-Myc levels and chlamydial growth in primary infections." (PMID 36155135, 2022). "To test this hypothesis, we silenced STAT1 and subsequently activated autophagy by rapamycin treatment after infection with mAIEC or pHRhodo particles." (PMID 33563644, 2022). "We therefore tested whether LgyLRV1+ infection led to phosphorylation of STAT-1 at the S727 residue together with phosphorylation of P65 at S536." (PMID 36034693, 2022). "Concurrently, we observed robust ISGylation at 48 h post infection with STAT1 activation." (PMID 36439639, 2022). "Of these, the viral phosphatase vH1 is released into the cytoplasm immediately upon infection, where it might dephosphorylate STAT1, although this activity was shown only in vitro." (PMID 35182467, 2022). "Furthermore, infection of Stat1−/− mice with Mtb also resulted in the accumulation of IL-18Rα+ ILC and a 3-fold reduction in ILC1-like cell generation." (PMID 35443177, 2022).
infection (continued). "Thus, in our model, it is possible that T cell-intrinsic STAT1-dependent IFN signaling also drives T follicular helper proliferation during MHV68 infection." (PMID 35968944, 2022). "While some studies showed that STAT1 is induced in epithelial cells upon H. pylori infection, other studies claimed a reduction of the activation of STAT1 upon infection with H. pylori strains proficient in a type IV secretion system and Cytotoxin associated gene A (CagA)." (PMID 35456965, 2022). "Other than N-RNA, P protein interacts with multiple cellular proteins with interaction with STAT1 shown to be highly significant to infection and pathogenesis through enabling suppression of antiviral STAT1 signaling via a critical binding site within the PCTD." (PMID 34237115, 2021). "However, some STAT1 partial loss of function (LOF) patients suffer from chronic colitis, as well as severe infections." (PMID 34378531, 2021). "STAT1 is typically activated in response to RV in epithelial cells and activates a signalling cascade that promotes the expression of anti-viral genes as part of the multifaceted epithelial response to infection." (PMID 34912343, 2021). "Those with AD STAT1 LOF mutations were susceptible to infection by mycobacteria but not by viruses, this is due to varying injury IFN-γ and IFN-α/β responses." (PMID 33777053, 2021). "Following infection with vF13L-HA, all STAT1-/- mice died by 8 days post-infection." (PMID 34962975, 2021). "This is evident by a failure to properly induce p-STAT1(Y701) upon PVSRIPO infection." (PMID 33849973, 2021). "We propose that STAT1-dependent Ly6Chi cells recruited by T. crassiceps infection may be the precursors that give rise to M2 macrophages during the chronic phase of the infection." (PMID 34684235, 2021). "In STAT1 knockout mice, infection of SARS-CoV results in severe disease." (PMID 33468694, 2021). "However, compared with the control group, 10 nM RAPA significantly inhibited p-STAT1 expression with non-infection." (PMID 34367129, 2021). "Importantly, inhibition of STAT1 contributes to the pathogenicity of all five viruses, evaluated through infection of STAT1 knockout mice or using mutant virus unable to target STAT1." (PMID 33477334, 2021). "Our results are consistent with the hypothesis that restriction factors such as IRF1, MX1, STAT1, C18orf25 limit lytic infection." (PMID 33914843, 2021). "Instead, we found that STAT1−/− mice were more resistant to this infection." (PMID 34684235, 2021). "In order to determine whether F514I-mediated attenuation in the WT intestine was associated with a failure to persist, we analyzed CR6 and CR6F514I infection in WT and Stat1-/- mice to 21 dpi." (PMID 33705489, 2021). "By focusing on the two macrophage states detected 8 h after the infection, we found the first state to be characterized by the module containing Irf7, Hmga1, Zfp275, and Stat1 that has been previously shown to initiate the inflammatory response to pathogens in an interferon gamma dependent manner." (PMID 34404761, 2021). "In summary, STAT1 is an important transcription factor involved in the response to IFN-γ but it also participates in the recruitment of inflammatory monocytes to the site of the infection and the spleen." (PMID 34684235, 2021). "GM-CSF inhibits IFNγ via STAT1; this might be the reason for low IFNγ in secondary infection, which needs to be studied." (PMID 34447698, 2021). "STAT1−/− mice displayed lower parasite burdens at 8 weeks post-infection compared to STAT1+/+ mice." (PMID 34684235, 2021). "Thus, we obtained sera from infected STAT1−/− mice 8 weeks post-infection and compared their cytokine levels to equally infected STAT1+/+ mice." (PMID 34684235, 2021).